ZFP36L1 (ZFP36 like 1 zinc finger CCCH-type)
Diseases named in the same sentence as ZFP36L1 in open-access papers (continued):
Sharing a sentence is not in itself a finding about the gene and the disease.
infection (continued). "We conclude that the absence of ZFP36 and ZFP36L1 in T cells does not promote immunopathology, but rather increases resilience following infection with a pathogenic virus." (PMID 35477960, 2022). "This together with our findings that ZFP36L1 expression in the whole lung decreases in response to infection, while its expression in macrophages is increased, suggests that other cell types may be a more important source of ZFP36L1 in the lung." (PMID 25299049, 2014). "As a potential reason for this clear lack of phenotype, we sought to determine ZFP36L1 expression patterns in the whole lung to determine whether other cells that contribute to an integrated host response to infection are also sources of ZFP36L1." (PMID 25299049, 2014). "Surprisingly, we found that myeloid deficiency of ZFP36L1 did not result in alteration of lung cytokine production after infection, altered clearance of bacteria, or increased inflammatory lung injury." (PMID 25299049, 2014). "With the finding that ZFP36L1 is induced during infection in alveolar macrophages, we next sought to evaluate whether NF-κB signaling pathway plays a role in the rapid induction of ZFP36L1." (PMID 25299049, 2014). "Interestingly, in this present study, whereas PCPEC displayed a strong inflammatory response to infection, genes attributed to hypoxia were found to play a more prominent role during infection in HIBCPP cells (including ZFP36L1, MXI1, KLHL24, PNRC1, CDKN1C, and DUSP2)." (PMID 33763387, 2021). "Knockdown of ZFP36L1 via infection of Ad-shZFP36L1 abrogated the IL-1β-induced upregulation of these matrix-degrading enzymes, suggesting that they could be direct targets of ZFP36L1." (PMID 30622281, 2019). "Despite the lack of increased cytokines in the lung at baseline in the ZFP36L1 deficient mice, we hypothesized that we would observe a difference in cytokine expression under stimulated conditions such as early after infection." (PMID 25299049, 2014). "Cells overexpressing ZFP36L1, ZFP36L2, or EGFP were infected with JEV and DENV at a high MOI, and the viral load and protein expression levels were measured at 24 h post-infection (hpi)." (PMID 39972499, 2025). "Wild type, ZFP36L1 overexpressed, and ZFP36L1 knockdown cells were each infected with HCoV-OC43, and the virus titer in each cell line was measured over 96 hours post-infection (p.i.)." (PMID 36846448, 2023). "Expression of viral latent proteins after infection amplified the viral effects on p38 and MK2, but also on ZFP36L1, altogether resulting in a transitory and limited increase in IL-6 and TNFα transcription and release." (PMID 37830871, 2023). "Contrary to ZFP36L1 expression, levamisole‐induced down‐regulation of PPARGC1B was completely compensated by PPARGC1B up‐regulation resulted from lenti‐shZFP36L1 infection (d vs c, b vs c)." (PMID 29993187, 2018). "All three ZFP36-family paralogues can be expressed by T cells, and, in the absence of infection or inflammation, ZFP36L1 is the most abundant in Treg cells and exerts non-redundant essential functions that are compensated partially by ZFP36L2." (PMID 40328742, 2025). "The limiting of autocrine IL‐2 production and the simultaneous de‐repression of IL‐2 signaling suggests that ZFP36L1 enforces dependence of CD8 T cells on paracrine IL‐2, which becomes available during the early phase of an infection and is largely produced by antigen‐specific CD4 T cells and DCs." (PMID 38039407, 2024). "We found that, in the absence of BBLF1 or BGLF2, and to a lesser extent BKRF4, p38/MK2 and ZFP36L1 failed to be activated upon infection." (PMID 37830871, 2023). "Unlike ZFP36 expression, ZFP36L1 levels are maximal under normal conditions and reduced during an infection time course." (PMID 25299049, 2014).
infection (continued). "To determine whether ZFP36/ZFP36L1 were limiting factors for cytotoxic CD4+ T cells in vivo, we infected Zfp36fl/fl/Zfp36l1fl/flCd4cre mice with influenza A virus (PR8 H1N1) and measured CD4+ T cells in the lung 10 days following infection." (PMID 36385275, 2022). "However, in response to infection, male mice exhibited higher expression levels of CXCL2 (KO, 1A3, and 6A2), SAMHD1 (1A0, 1A3), RSAD2, STAT1, and STAT3 (1A0), MYD88 and PSMB8 (1A3), BCL3, BCL10, CCRL2, IFITM2, RTP4, and ZFP36L1 (6A2), compared to females." (PMID 32670284, 2020). "qRT‐PCR analysis revealed that lenti‐shZFP36L1 infection remarkably decreased ZFP36L1 mRNA expression which resulted in significant up‐regulation of the mRNA levels of the adipogenic differentiation markers (PPARγ, PLIN1, LPL and FABP4) as compared with the lenti‐control (lenti‐ctrl) infection." (PMID 29993187, 2018). "Western blot analysis revealed that lenti-shZFP36L1 infection remarkably decreased ZFP36L1 expression which resulted in significant down-regulation of the mRNA levels of the monocyte/macrophage differentiation markers (CD11B, CD14 and CSF1R) as compared with the lenti-control (lenti-ctrl) infection." (PMID 26542173, 2015). "Because myeloid-deficient ZFP36 mice exhibit a prominent spontaneous inflammatory disorder, we first investigated ZFP36L1 mutant mice in the absence of infection to determine whether they have heightened levels of inflammation at baseline." (PMID 25299049, 2014). "Similar to the in vitro results, ZFP36L1 and ZFP36 expression was induced by E. coli, although induction was highest 6 hours post infection (Data not shown)." (PMID 25299049, 2014).
Bacterial Infection (2 papers, 2014 to 2022). "Thus, in model viral and bacterial infections, Zfp36 and Zfp36l1 function within CD8+ T cells to delay the onset of differentiation and limit the magnitude of acquired effector functions." (PMID 35477960, 2022).
ZFP36L1 also shares sentences with these, for which no sentence is quoted: hepatocellular carcinoma (2 papers); lymphoma (2); adenocarcinoma (1); adrenocortical carcinomas (1); aplastic anaemia (1); Atrophy (1); autoimmune disease (1); chronic obstructive pulmonary disease (1); chronic rhinosinusitis (1); diabetic retinopathy (1); Hepatic steatosis (1); Hypercholesterolemia (1); hypothyroidism (1); Insulin resistance (1); iron deficiency (1); ischemic stroke (1); leprosy (1); liver cancer (1); lung carcinoma (1); nasopharyngeal carcinoma (1); neuroendocrine tumors (1); non-small cell lung carcinoma (1); ovarian carcinoma (1); Sepsis (1); small cell lung carcinoma (1); steatosis (1); triple-negative breast carcinoma (1); uterus carcinomas (1).